FNDC3B (fibronectin type III domain containing 3B)
Diseases named in the same sentence as FNDC3B in open-access papers (continued):
Sharing a sentence is not in itself a finding about the gene and the disease.
cancer (continued). "We used TIMER2.0 to explore the relationship between FNDC3B with the top 10 most significantly up or downregulated DEGs in pan-cancer." (PMID 36275754, 2022). "High expression of FNDC3B was discovered in 52 studies of 13 cancers, and its low expression was only found in 4 cancers and 16 studies." (PMID 36626432, 2022). "FNDC3B promotes epithelial-to-mesenchymal transition and activates multiple cancer pathways, for example, in squamous cell carcinoma, acute promyelocytic leukemia, and hepatocellular carcinoma." (PMID 31093274, 2019). "Studies have shown that the homozygous disruption of FNDC3B has a lethal effect on the migration of mouse embryo fibroblasts and that FNDC3B participates in several cancer pathways." (PMID 30963578, 2019). "The Fndc3b gene has been shown to be elevated in different types of cancers and exhibits a role in survival signaling, and we reveal that exogenous delivery of circFndc3b can play an important role in attenuating left ventricular dysfunction after MI in mice." (PMID 31541092, 2019). "And up-regulation of miR-143 expression transcribed by nuclear factor kappa B (NF-кB) promotes cancer cell invasion and metastasis by repression of FNDC3B expression." (PMID 25408705, 2014). "However, several non‐coding RNAs have been found to regulate FNDC3B expression in other cancers recently." (PMID 38403291, 2024). "Emerging evidence suggests that several circRNAs derived from FNDC3B play pivotal roles in cancer." (PMID 38802851, 2024). "Some circRNAs implicated in oxidative stress and inflammation-related disorders are circ-PRKCA, circ-ZNF83, circ-PLEKHM3, circ-FNDC3B, circ-102115 circSATB2 and circFOXM1 on which natural products modulation have been investigated in cancers and other disorders." (PMID 37168992, 2023). "In this study, we investigated the expression of FNDC3B in cancers of 20 different organs and the overall survival related to FNDC3B expression levels in GBM using Oncopression database analysis to validate the potential of FNDC3B as an effective prognostic and therapeutic biomarker for GBM." (PMID 38137388, 2023). "Other ncRNAs involved in oxidative stress and inflammation-related disorders are circular RNAs such as circ-PRKCA, circ-ZNF83, circ-PLEKHM3, circ-FNDC3B, circ-102115 circSATB2 and circFOXM1 on which natural products modulation have been investigated on in cancers and other chronic diseases." (PMID 37168992, 2023). "Moreover, we investigated the associations between FNDC3B expression and immune subtypes across human cancers, and the landscape of correlations between FNDC3B expression and immune subtypes in different types of cancer." (PMID 36275754, 2022). "Similarly, the 3′ UTR of RAC1 and Fibronectin type III domain containing 3B (FNDC3B) is shortened which results in enhanced protein production during cancer progression." (PMID 36114510, 2022). "Moreover, we analyzed the relationships between FNDC3B expression and prognostic values in 33 types of cancer using GEPIA2 databases." (PMID 36275754, 2022). "Furthermore, we investigated the correlation between FNDC3B with cancer immune infiltrates using TISIDB, ESTIMATE, and CIBERSORTx." (PMID 36275754, 2022). "Consistent with its oncogenic role in multiple cancer types, the overexpression of FNDC3B could malignantly transform mammary and kidney epithelial cells and hepatocytes." (PMID 32972270, 2020). "Finally, disease-free survival analysis of cancer patients indicated that overexpression of FNDC3B correlates with recurrence and metastasis." (PMID 27385217, 2016). "FNDC3B has also been identified in an oncogenomic screen for amplified oncogenes, and over-expression of FNDC3B induces epithelial-to-mesenchymal transition and activates several cancer pathways." (PMID 25823933, 2015). "However, the prognostic significance and functional role of FNDC3B in cancer remain unexplored." (PMID 38303056, 2024).
cancer (continued). "Therefore, it can be considered that FNDC3B may serve as a valuable prognostic biomarker across pan-cancer." (PMID 38581008, 2024). "Since previous studies have reported that TILs are independent predictors in cancers, we used TISIDB database to infer the correlations between the expression of FNDC3B and the abundance of 27 types of TILs across TCGA pan-cancers." (PMID 36275754, 2022). "FNDC3B is contained in the amplified region 3q26.1-q27.2, inducing the epithelial-to-mesenchymal transition (EMT) and activating several cancer pathways, including PI3-kinase/Akt, RB1 and TGFβ signaling." (PMID 26901676, 2016). "Oncomine revealed that the mRNA expression levels of FNDC1, FNDC3A, and FNDC3B were higher in most malignancies than in normal tissues, but the mRNA expression levels of FNDC4, FNDC5, FNDC7, and FNDC8 were downregulated in most cancers when compared with normal tissues." (PMID 36626432, 2022). "Regarding FNDC3B, only 1 out of 34 analyses showed significantly increased expression between the cancer and non-cancerous groups." (PMID 36626432, 2022). "Additionally, the biological function of FNDC3B and BPGM in regulating cancer cell proliferation, invasion, and therapy resistance needs to be clarified." (PMID 34976823, 2021). "First, FNDC3B is usually amplified and highly expressed in HCC and other cancers." (PMID 27385217, 2016).
blood cancers (1 paper, 2022). "Moreover, the expression of FNDC3A, FNDC3B, FNDC5, and FNDC6 has been implicated in the prognosis of blood cancers." (PMID 36626432, 2022).
cardiovascular diseases (1 paper, 2024). "However, the roles of UNC119B, RERE, and FNDC3B in cardiovascular diseases are not known." (PMID 38303056, 2024).
infection (1 paper, 2018). The state of being infected such as from the introduction of a foreign agent such as serum, vaccine, antigenic substance or organism. "We found that infection with Jad/C(4fC) resulted in the significant upregulation of c-MYC (P < 4 × 10−6), TBX3 (P < 0.0006), AXIN2 (P < 0.0068), FNDC3B (P < 1 × 10−5), FASN (P < 0.0005) and CCND1 (P < 0.0002), with c-MYC and TBX3 showing the highest upregulation levels." (PMID 30046100, 2018).
FNDC3B also shares sentences with these, for which no sentence is quoted: colon adenocarcinoma (2 papers); esophageal cancer (2); lung adenocarcinoma (2); open-angle glaucoma (2); skin cutaneous melanoma (2); squamous cell carcinoma (2); bladder urothelial carcinoma (1); brain glioma (1); cholangiocarcinoma (1); connective tissue disorder (1); COVID-19 (1); diabetes (1); endocervical adenocarcinoma (1); epilepsy (1); head and neck squamous cell carcinoma (1); kidney (1); major depressive disorder (1); mesothelioma (1); Obesity (1); ovarian carcinoma (1); pancreatic adenocarcinoma (1); Parkinson disease (1); pilocytic astrocytoma (1); primary angle-closure glaucoma (1); stomach adenocarcinoma (1); testicular germ cell tumor (1); uterine corpus endometrial carcinoma (1); uveal melanoma (1); virus infection (1).